MAFG (MAF bZIP transcription factor G)
Description:
Since they lack a putative transactivation domain, the small Mafs behave as transcriptional repressors when they dimerize among themselves. However, they seem to serve as transcriptional activators by dimerizing with other (usually larger) basic-zipper proteins, such as NFE2, NFE2L1 and NFE2L2, and recruiting them to specific DNA-binding sites. Small Maf proteins heterodimerize with Fos and may act as competitive repressors of the NFE2L2 transcription factor. Transcription factor, component of erythroid-specific transcription factor NFE2L2. Activates globin gene expression when associated with NFE2L2. May be involved in signal transduction of extracellular H(+) (By similarity).
Synonyms: MGC13090; MGC20149; hMAF
Tractability: PROTAC: UniProt records ubiquitination sites on it; ubiquitination databases record sites on it; its protein half-life has been measured.
Target class: Transcription factor
Gene: Protein-coding gene on chromosome 17 (81,918,270 to 81,927,735, reverse strand). Ensembl gene ENSG00000197063.
Subcellular location: Nucleus
Pathways (Reactome):
Cellular responses to stimuli: NFE2L2 regulates pentose phosphate pathway genes; Nuclear events mediated by NFE2L2
Hemostasis: Factors involved in megakaryocyte development and platelet production
Gene Ontology:
Molecular function: identical protein binding; protein binding; sequence-specific double-stranded DNA binding; DNA-binding transcription factor activity; DNA-binding transcription factor activity, RNA polymerase II-specific; RNA polymerase II cis-regulatory region sequence-specific DNA binding; DNA binding; DNA-binding transcription activator activity, RNA polymerase II-specific
Biological process: negative regulation of transcription by RNA polymerase II; regulation of epidermal cell differentiation; regulation of transcription by RNA polymerase II; positive regulation of gene expression; positive regulation of transcription by RNA polymerase II; regulation of DNA-templated transcription
Cellular component: nucleus; RNA polymerase II transcription regulator complex; nucleoplasm
Genetic constraint (gnomAD): Loss-of-function variants: 3 observed, 9.61 expected, observed/expected ratio (o/e) 0.31, 90% interval 0.14 to 0.81. That is too few expected variants to judge how well the gene tolerates losing a copy. Missense variants: 153 observed, 203.89 expected, observed/expected ratio (o/e) 0.75, 90% interval 0.66 to 0.86. Synonymous variants: 126 observed, 100.67 expected, observed/expected ratio (o/e) 1.25, 90% interval 1.08 to 1.45.
Homologues: Orthologues: chimpanzee MAFG (100% identical), macaque MAFG (100% identical), dog MAFG (99% identical), mouse Mafg (99% identical), guinea pig MAFG (98% identical), pig MAFG (98% identical), zebrafish mafgb (91% identical), zebrafish mafga (89% identical), Drosophila melanogaster tj (36% identical), Drosophila melanogaster maf-S (35% identical), Caenorhabditis elegans maf-1 (30% identical). Paralogues in human: MAFK (73% identical), MAFF (62% identical), MAF (43% identical), MAFB (40% identical), MAFA (39% identical), NRL (33% identical).
Diseases named in the same sentence as MAFG in open-access papers:
MAFG is named in the same sentence as 54 diseases in open-access papers, as found by Europe PMC text mining. Sharing a sentence is not in itself a finding about the gene and the disease. The quoted sentences say what the papers report.
melanoma (7 papers, 2017 to 2025). A malignant, usually aggressive tumor composed of atypical, neoplastic melanocytes. "In melanoma cell lines, MAFG is markedly upregulated, highlighting its essential involvement in melanoma progression." (PMID 41316357, 2025). "Immunostaining of human melanoma samples (n = 14) also showed a positive correlation between MAFG and tumor pathological grade." (PMID 37614365, 2023). "Our work uncovered that miR-29 constrains MAPK pathway-driven melanoma formation, at least in part, by repressing MAFG and MYBL2." (PMID 33808771, 2021). "First, we analyzed MAFG expression in melanocytes and melanoma cell lines and found that MAFG mRNA levels are increased in melanoma cell lines." (PMID 33808771, 2021). "Our findings suggest that attenuation of miR-29b2~c expression promotes melanoma development, at least in part, by derepressing MAFG and MYBL2." (PMID 33808771, 2021). "MAFG protein expression was similarly elevated in melanoma cell lines compared to melanocytes." (PMID 33808771, 2021). "We next assessed if the expression of MAFG is altered during melanoma development." (PMID 33808771, 2021). "In addition, we observed slightly increased MAFG protein levels in bulk melanomas from miR-29 sponge chimeras compared to GFP control mice." (PMID 33808771, 2021). "Thus, MAFG is deregulated in melanoma through multiple mechanisms and miR-29-mediated repression of MAFG may impair the transition from nevi to frank melanoma." (PMID 33808771, 2021). "Therefore, our in vivo validation that miR-29 is a tumor suppressive miRNA in melanoma might contribute to the development of new therapeutic approaches, not only targeting MAFG or MYBL2, but also miR-29 itself." (PMID 33808771, 2021). "However, whether this epigenetic gene expression regulation and/or additional transcription factor complexes involving MAFG play critical roles in melanoma formation is unknown." (PMID 33808771, 2021). "Interestingly, however, MAFG is an epigenetic regulator and transcriptional repressor in melanoma and hyperactive MAPK may increase MAFG stability by ERK-mediated phosphorylation." (PMID 33808771, 2021). "In addition to being repressed by miR-29, TCGA data indicate copy number gains of MAFG in melanoma." (PMID 33808771, 2021). "Moreover, we validated MAFG as bona fide target of miR-29 in melanoma." (PMID 33808771, 2021). "In melanoma, oncogenic BRAFV600E has been shown to stabilize MAFG, resulting in the recruitment of an epigenetic repressor complex to promoters and transcriptional silencing." (PMID 33808771, 2021). "Future studies will address if overexpression of MAFG or MYBL2 contributes to melanocyte transformation and melanoma development." (PMID 33808771, 2021). "To validate MAFG as a target of miR-29, we transfected miR-29a, miR-29b, or miR-29c mimics into BRAFV600E-expressing melanocytes (H1B) and melanoma cells (WM164)." (PMID 33808771, 2021). "We further identify the transcription factors MAFG and MYBL2 as targets of miR-29 and show that their repression is detrimental for melanoma cells." (PMID 33808771, 2021). "Through integrated RNA sequencing, target prediction, and functional assays, we identified the transcription factors MAFG and MYBL2 as bona fide miR-29 targets in melanoma." (PMID 33808771, 2021). "In colorectal cancer and melanoma, BACH1 heterodimerizes with MAF BZIP Transcription Factor G (MAFG), cooperating with chromodomain helicase DNA-binding protein 8 (CHD8) and DNA Methyltransferase 3 Beta (DNMT3B) to inhibit the transcription of many antioncogenes." (PMID 35651942, 2022). "We next sought to validate MAFG and MYBL2 as targets of miR-29 in melanoma." (PMID 33808771, 2021). "Targeting MAFG- and MYBL2-regulated processes may therefore represent a promising therapeutic strategy to treat miR-29-low melanoma." (PMID 33808771, 2021). "De-repression of MAFG and MYBL2, which we identified as bona fide targets of miR-29, may contribute to melanoma development." (PMID 33808771, 2021).
melanoma (continued). "Knockdown of MAFG and, to a lesser extent, MYBL2 significantly decreased proliferation and focus formation of A375 melanoma cells, suggesting that miR-29 may suppress melanoma by targeting these two genes." (PMID 33808771, 2021). "Finally, we identified MAFG and MYBL2 as miR-29 targets whose de-repression may be critical for melanoma development." (PMID 33808771, 2021).
cholangiocarcinoma (6 papers, 2019 to 2023). A carcinoma that arises from the intrahepatic biliary tree (intrahepatic cholangiocarcinoma) or from the junction, or adjacent to the junction, of the right and left hepatic ducts (hilar cholangiocarcinoma). "The expression of MAfG increases in cells and tissues with cholestasis, as well as in human cholangiocarcinoma and HCC, and correlates with tumor progression and decree (sed survival time." (PMID 35159219, 2022). "Previous studies showed that MAFG contributed to the malignant progression of cholangiocarcinoma, colorectal cancers and chemotherapy resistance 15, 25, acting as an oncoprotein." (PMID 34976178, 2022). "Liu and co-workers observed that MAFG is positively correlated with the progression of tumour cells especially in patients with cholangiocarcinoma and hepatocellular carcinoma." (PMID 33124660, 2020). "The expression of MAfG (MAF bZIP transcription factor G) increases in cells and tissues with cholestasis, as well as in human cholangiocarcinoma and HCC in which MAFG overexpression correlates with tumor progression and reduced survival time." (PMID 35159219, 2022). "c-Myc induction drives cholestatic liver injury and cholangiocarcinoma (CCA) in mice, and the induction of Maf proteins (MafG and c-Maf) contributes to cholestatic liver injury, whereas SAM administration could be protective." (PMID 35159219, 2022). "In human hepatocellular carcinoma (HCC) and cholangiocarcinoma (CCA) cells, PHB1 inhibits cell growth and negatively regulates the expression of oncogenes c-MYC, MAFG, and c-MAF." (PMID 30886235, 2019).
colorectal cancer (6 papers, 2018 to 2025). A primary or metastatic malignant neoplasm that affects the colon or rectum. "BRAFV600E-stabilized MAFG initiated recruitment of a co-repressor complex to CpG island methylator phenotype (CIMP) gene promoters in colorectal cancer cells, which is associated with tumorigenesis and cancer growth." (PMID 33868783, 2021). "On the contrary, functional silencing of MAFG could repress the liver homing of tumor cells in colorectal cancer, indicating its promoting roles in metastasis and liver colonization in colorectal cancer." (PMID 36685838, 2022). "Silencing of MAFG potently inhibited colorectal cancer cell growth." (PMID 33868783, 2021). "Therefore, our findings indicate that elevated YBX1 protein levels may promote colorectal cancer progression by recognizing and stabilizing oncogenic transcripts such as EREG, MAFG, and GAS6, thereby activating downstream signaling pathways involved in tumorigenesis." (PMID 40819060, 2025).
hepatocellular carcinoma (6 papers, 2011 to 2024). A malignant tumor that arises from hepatocytes. "The overexpression of MAFG in hepatocellular carcinoma is associated with tumor progression and decreased survival." (PMID 33868783, 2021).
breast carcinoma (4 papers, 2022 to 2023). "Immunostaining of primary human breast cancer samples (n = 12) revealed that MAFG was negatively correlated with nuclear YAP and positively correlated with the tumor pathological grade." (PMID 37614365, 2023). "MAFG is also positively correlated with PD-L2 in breast cancer." (PMID 37985752, 2023). "In breast cancer, the expression of MAFG is positively correlated with the expression of PD-L1." (PMID 37985752, 2023). "Across breast cancer cell lines, MAFG exhibited a strong correlation with PD-L1." (PMID 37985752, 2023). "MafG accelerates cell proliferation and inhibits cell apoptosis in lung adenocarcinoma, while MafF promotes tumor invasion through heterodimerizing with Bach1 and activating the IL11/STAT3 pathway in breast cancer." (PMID 37491302, 2023).
fibrosarcoma (4 papers, 2020 to 2023). A malignant mesenchymal fibroblastic neoplasm affecting the soft tissue and bone. "In contrast, lncRNA promoters were enriched for MAFG:NFE2L1 (V-Maf Avian Musculoaponeurotic Fibrosarcoma Oncogene Homolog G:Nuclear Factor, Erythroid 2 Like 1) motifs." (PMID 32005828, 2020). "The small musculoaponeurotic fibrosarcoma (sMaf) proteins MafF, MafG, and MafK are basic region leucine zipper- (bZIP-) type transcription factors and display tissue- or stimulus-specific expression patterns." (PMID 33488846, 2020).
non-small cell lung carcinoma (4 papers, 2021 to 2023). A group of at least three distinct histological types of lung cancer, including non-small cell squamous cell carcinoma, adenocarcinoma, and large cell carcinoma. "miR-4660 and miR-7 that directly contact the 3’ untranslated region of MafG mRNA suppress osteosarcoma cell growth and chemosensitivity to cisplatin in non-small-cell lung cancer (NSCLC) respectively." (PMID 36750911, 2023). "It has been clearly reported that MAF BZIP Transcription Factor G (MAFG) has a promising potential as a potential prognostic biomarker in non-small cell lung cancer." (PMID 36226171, 2022). "In non-small cell lung cancer, MAFG inhibition or downregulation induced ROS production, sensitizing cancer cells to cisplatin-induced apoptosis." (PMID 33868783, 2021).
Thrombocytopenia (3 papers, 2010 to 2020). A reduction in the number of circulating thrombocytes. "These mutant mice develop more severe deficiencies in megakaryopoiesis compared with MafG-null mice, specifically in proplatelet formation, resulting in profound thrombocytopenia." (PMID 28899199, 2018). "Gene targeting of MafF and MafK does not cause any apparent phenotype, while MafG-null mice exhibit abnormal megakaryocyte differentiation and thrombocytopenia accompanied by a late-onset neurological disorder." (PMID 28899199, 2018). "In fact, thrombocytopenia driven by recombinant IFN α has been related to the selective inhibition of cytoplasmic maturation accompanied by downregulation of the expression of the transcription factors NF-E2, GATA-1 and MafG/HPRT." (PMID 20419155, 2010).
experimental autoimmune encephalomyelitis (2 papers, 2023 to 2024). An autoimmune demyelinating disease of the central nervous system that is produced experimentally in animals by the injection of homogenized brain or spinal cord in Freund's adjuvant. "Specifically, a recent study identified that MAFG-driven astrocytes promote CNS inflammation and repress antioxidant and anti-inflammatory transcriptional modules in MS and its preclinical model, experimental autoimmune encephalomyelitis (EAE)." (PMID 37189441, 2023). "Some astrocytes are characterized by reduced gene expression driven by NRF2 and increased signaling of MAFG and MAT2a, promoting central system inflammation in experimental autoimmune encephalomyelitis, which may lead to the pathogenesis of MS." (PMID 39440247, 2024).
Hyperglycemia (2 papers, 2020 to 2022). An increased concentration of glucose in the blood. "We further observe that obesity-repressed LincIRS2 is negatively controlled by MAFG and CRISPR–Cas9-mediated knockout, or antisense-mediated RNA interference of LincIRS2 causes hyperglycemia, insulin resistance, likely caused by alterations in glucogenic gene expression in lean mice." (PMID 32005828, 2020). "However, there are few studies related to MAFG in the pathogenesis of DFU progression, and only a few reports suggest that MAFG loss improves glucose metabolism and insulin sensitivity, thus protecting from hyperglycemia." (PMID 36226171, 2022).
lung carcinoma (2 papers, 2010 to 2020). "We hypothesize that reduced MAFG levels and the subsequent reduction in the protective oxidative stress response may represent a gene expression hallmark in bronchial epithelial cells of smokers who develop lung cancer." (PMID 20689807, 2010). "A SNP at chr17:77482956 in the MAFG promoter region was associated with lower MAFG mRNA levels, while another in the 3′ UTR displayed a marginal association with expression and lung cancer status." (PMID 20689807, 2010). "This novel observation suggests that reduced levels of MAFG and higher levels of NRF1 (negative regulator) may be suppressing the transcription of these ARE-regulated genes among smokers who go on to develop lung cancer." (PMID 20689807, 2010).
Obesity (2 papers, 2020 to 2024). Accumulation of substantial excess body fat. "Conversely, postprandial or obesity-associated activation of MAFG would trigger energy-demanding, anaplerotic processes like an increase in cellular proliferation and protein synthesis as a consequence of mTOR-4E-BP1 pathway activation." (PMID 32005828, 2020). "In vitro and in vivo loss of MAFG in hepatocytes controls glucose production, improves glucose metabolism during obesity, and induces lncRNAs, whereas MAFG gain of function represses hepatic lncRNAs." (PMID 32005828, 2020). "Mechanistically, we demonstrated that MAFG controls a specific set of obesity-associated hepatic lncRNAs that are repressed in obese livers, in addition to the known function of MAFG in bile acid regulation." (PMID 32005828, 2020). "In silico analyses of lncRNA and mRNA promoters, and integration of MAFG ChIP-Seq with MAFG gain-of-function RNA-Seq data confirm that elevated MAFG signaling in obesity and RF is transcriptionally linked to lncRNA repression." (PMID 32005828, 2020). "We find that obesity-repressed LincIRS2 is controlled by MAFG and observe that genetic and RNAi-mediated LincIRS2 loss causes elevated blood glucose, insulin resistance and aberrant glucose output in lean mice." (PMID 32005828, 2020). "The lncRNA MIST was downregulated in response to proinflammatory stimuli, exhibiting an inverse correlation with obesity and insulin resistance while lincIRS2 was downregulated in induced obesity mediated by the transcription factor MAFG." (PMID 38668382, 2024). "Our results establish the TF MAFG as a regulator of energy-rich nutrient states in the liver, both in postprandial responses and during metabolic diseases like obesity and type 2 diabetes." (PMID 32005828, 2020).
prostate carcinoma (2 papers, 2011 to 2022). A carcinoma that arises from epithelial cells of the prostate gland. "We then explored the effect of MAFG on the malignant phenotype of prostate cancer cells." (PMID 34976178, 2022). "Thus, in this study, we provided evidence for a novel link between MAFG and EIF3J-AS1 in prostate cancer." (PMID 34976178, 2022).
Sepsis (2 papers, 2023). Sepsis is defined as life-threatening organ dysfunction caused by a dysregulated host response to infection. "BCL9L, BCL11B, CD247, CD96 and SAMD3 were decreased in sepsis and mainly expressed in the T cell; while MAFG increased in sepsis and localizes to monocytes." (PMID 36918563, 2023). "The expression of MAFG was lower in sepsis and normal group." (PMID 36918563, 2023). "MAFG was increased in sepsis samples, compared with the normal group." (PMID 36918563, 2023).
Ad- (1 paper, 2021). "Consistently, Ad-MAFG infection decreased the luciferase activities of the reporters containing Cyp7b1, Cyp8b1, and Cyp27a1 promoters in hepatocytes, respectively." (PMID 33754066, 2021).
bladder urothelial carcinoma (1 paper, 2023). "In addition, MAFG expression also negatively correlated with the survival of patients with liver hepatocellular carcinoma (n = 374), uterine corpus endometrial carcinoma (n = 552), lung squamous cell carcinoma (n = 502), bladder urothelial carcinoma (n = 414), and esophageal carcinoma (n = 162)." (PMID 37614365, 2023).
breast tumor (1 paper, 2023). "Considering the induction of MAFG expression in the fibrin-based mechanical environment, here we also analyzed fibrinogen levels in clinical breast tumor samples (n = 12)." (PMID 37614365, 2023).
Cholestatic liver disease (1 paper, 2021). "Given that several miRNA-based therapeutics have advanced into clinical testing, it would be interesting to test whether overexpression of hepatic miR-378 could improve cholestatic liver disease by downregulating MAFG in the future." (PMID 33754066, 2021).